BRAF (B-Raf proto-oncogene, serine/threonine kinase)
Diseases named in the same sentence as BRAF in open-access papers (continued):
Sharing a sentence is not in itself a finding about the gene and the disease.
metastatic melanoma (continued). "In one report, a patient with triple wild-type (BRAF/NRAS/NF1 WT) metastatic melanoma with two missense mutations in MAP2K1 showed a partial response to MEK inhibitor trametinib, followed by progression of disease after two months." (PMID 32483240, 2020). "Considerable debate exists regarding the optimal sequence of treatment with targeted therapies and immunotherapies for patients with BRAF-mutated metastatic melanoma." (PMID 32746839, 2020). "Even though BRAF monotherapy (BRAFi), or its combination with MEK inhibitors (MAPKi) instigate a profound regression in patients with BRAF-mutated metastatic melanoma, their effect is only temporary." (PMID 33203119, 2020). "The same team performed a study on 16 patients with BRAF-mutation positive metastatic melanoma treated by a combination of vemurafenib and ipilimumab with longitudinal 18F-FDG PET/CT for the follow-up." (PMID 32041105, 2020). "Another study of 146 patients in Lebanon (Asia) also reported the presence of subcutaneous metastatic melanoma correlated to the presence BRAF mutations." (PMID 31274706, 2020). "Routine circulating DNA testing is easy and is currently being performed in our hospital for some patients with newly diagnosed metastatic melanoma, to allow a rapid initiation of targeted therapy if a BRAF mutation is identified." (PMID 32664549, 2020). "These BRAF inhibitors are available in several countries for the treatment of BRAF-mutated metastatic melanoma." (PMID 32213878, 2020). "It would now be of great interest to evaluate the possible association between these SL metabolic alterations and the mutation status of oncogenes such as BRAF or NRAS as well as immune responses in metastatic melanoma patients." (PMID 32858889, 2020). "Data analysis from TCGA confirmed the increased expression of ZEB1-AS1 in metastatic melanoma and its association with hotspot mutations in BRAF and RAS family genes." (PMID 33203119, 2020). "On this basis, targeted therapies for the treatment of BRAF mutated, advanced, or metastatic melanoma were introduced in treatment protocols." (PMID 32695793, 2020). "The FDA again expanded the indication of this combination regimen to metastatic melanoma across BRAF mutation status on 23 January 2016 based on the improved progression-free survival (PFS) rate noted in the CheckMate-067 trial (Category 1)." (PMID 32245016, 2020). "Ten patients with metastatic melanoma with established driver BRAF or NRAS mutations were included in this study; 5/10 patients were aged 65 years or older, 8/10 were male and 6/10 had American Joint Committee on Cancer (AJCC) stage M1c disease." (PMID 31795494, 2019). "Between June 2013 and November 2014, 58 patients with BRAF-mutated metastatic melanoma began treatment with vemurafenib." (PMID 31231466, 2019). "Nevertheless, as a consequence of the diverse and contradictory information surrounding patient survival when analyzing both primary and metastatic melanomas, the prognostic value of BRAF mutations is still under discussion." (PMID 31835364, 2019). "The therapeutic options for the management of metastatic melanoma in BRAF-mutated patients have improved dramatically with the development of targeted and immune checkpoint based therapies." (PMID 31921863, 2019). "BRAF inhibitors (BRAFi, e.g. vemurafenib) improve survival for patients with metastatic melanomas harboring the BRAFV600E mutation." (PMID 31316083, 2019). "The combination of dabrafenib and trametinib was evaluated in BRAF mutated metastatic melanoma patients with brain metastases in the COMBI-MB trial." (PMID 30886831, 2019). "During last years the role of autophagy is emerging in anticancer therapy and also in the context of MAPKi inhibitors in BRAF-mutated metastatic melanoma." (PMID 30254376, 2019). "In conclusion, we proved that slightly cytotoxic doses of 5azadC are translated into an anti-invasive effect in a BRAF-mutated metastatic melanoma model." (PMID 30651148, 2019).
metastatic melanoma (continued). "Both inhibitors display anticancer activity against metastatic melanoma carrying the BRAF V600E/K mutation." (PMID 30252580, 2019). "The presence of somatic BRAF V600 mutations, for instance, is a clinically significant predictive biomarker for response to small‐molecule inhibitors of BRAF in patients with metastatic melanoma." (PMID 30536617, 2019). "In this paper we evaluate the performance of a previously developed serum proteomic test, BDX008, in metastatic melanoma patients treated with anti-PD-1 agents and investigate the role of BRAF mutation status." (PMID 30925943, 2019). "Approximately 50% of patients with metastatic melanoma have mutations in BRAF, and over 95% of these are in BRAF exon 15 at V600." (PMID 31653096, 2019). "In patients with BRAF-mutated metastatic melanoma treated with BRAF and MEK inhibitors, certain gene signatures have been identified as prognostic 10,16—the ‘immune’ gene signature being favourable and the ‘cell cycle’ being unfavourable." (PMID 31417188, 2019). "Indications have expanded since; they include metastatic melanoma with disease progression on ipilimumab and, if BRAF V600 mutation positive, a BRAF inhibitor, as well as adjuvant treatment following resection for stage III disease." (PMID 31640266, 2019). "BRAF V600E mutation specific treatment has improved the overall survival for patients diagnosed with metastatic malignant melanoma." (PMID 31181803, 2019). "Vemurafenib has long been approved for the treatment of metastatic melanoma with BRAF mutation, and our results showed that this drug had a damaging effect on the specific crosstalk of risk pathway of the luminal A subtype through action on hsa-miR-145." (PMID 31466383, 2019). "In our study we identified 12 downregulated and five upregulated plasma lncRNAs in BRAF-mutated metastatic melanoma compared to healthy individuals." (PMID 31231466, 2019). "The MEK inhibitors cobimetinib and trametinib are currently used in combination with BRAF inhibitors for treatment of metastatic melanoma carrying the BRAF V600E/K mutation." (PMID 30252580, 2019). "We reviewed the literature to assess the efficacy and risk of constitutional, cardiac, gastrointestinal, and dermatological toxicities of combined BRAF plus MEK inhibitors versus BRAF inhibitors alone in patients with metastatic melanoma with BRAF mutations." (PMID 31817473, 2019). "Drug resistance imposes severe limitations to the efficacy of targeted therapy in BRAF-mutated metastatic melanoma." (PMID 30254376, 2019). "This study focuses on the management of patients with mCRC, but KRAS, NRAS or BRAF mutations testing is also relevant in other cancers like metastatic melanoma or non-small cell lung cancer." (PMID 30811471, 2019). "This was based on results from the Phase I, II and III clinical studies (‘BRIM1’, ‘BRIM2’ and ‘BRIM3’, respectively) in people with BRAF V600E mutation-positive, inoperable or metastatic melanomas." (PMID 30975211, 2019). "Accordingly, there is a high clinical relevance of testing brain tumors for the presence of BRAF mutations/fusions as targeted therapies for BRAF aberrations are available with the clinical introduction for metastatic malignant melanoma." (PMID 31181803, 2019). "In this case report, we discuss a 33-year-old woman with BRAF V600E-mutated metastatic melanoma who presented in fulminant DIC with concurrent hemorrhagic and thrombotic manifestations and discuss the patient's brief response to combination therapy." (PMID 31093395, 2019). "A BRAF gene mutation was detected in five (8.3%) patients with metastatic melanoma and a C-MYC mutation was detected in one (1.7%) patient with non-Hodgkin lymphoma." (PMID 31429741, 2019). "Nearly half of patients with metastatic melanomas harbor a valine–glutamine substitution in codon 600 of the serine/threonine kinase BRAF (BRAFV600 mutation)." (PMID 31354491, 2019).
metastatic melanoma (continued). "These encouraging responses across all the cohorts make the combination of BRAF + MEK inhibitors a reasonable strategy in the management of patients with BRAF mutated metastatic melanoma with brain metastases." (PMID 30886831, 2019). "Using this approach, BRAF mutations were detected in 23 out of the 65 samples (35%), which is in line with the frequency of BRAF mutations in metastatic melanoma." (PMID 31415669, 2019). "As a last step, to strengthen our results, we selected four primitive cell lines derived from metastatic melanoma patients, three (Pt1, Pt2, Pt3) harboring the commonest BRAF mutation (V600E) and one (Pt4) the V600R BRAF mutation." (PMID 31115969, 2019). "Mutations in epidermal growth factor receptor (EGFR), and rearrangements of anaplastic lymphoma kinase (ALK) are targetable in lung cancer, while BRAF mutations have been successfully targeted in metastatic melanoma." (PMID 30886831, 2019). "Trametinib, a selective allosteric inhibitor of MEK kinase, has been clinically used to treat metastatic melanoma and non-small-cell lung cancer harbouring BRAF V600E mutations." (PMID 30833665, 2019). "In BRAF-mutated metastatic melanoma, a phase I–II clinical study assess the effect of DNA methylation on tumor progression and resistance development under therapy with BRAFi and MEKi with or without decitabine (NCT01876641)." (PMID 29794999, 2018). "Trametinib is a MEK1/2 inhibitor approved by the FDA in combination with dabrafenib for unresectable or metastatic melanoma and non–small-cell lung cancer carrying mutations in BRAF (V600E/V600K)." (PMID 30706044, 2018). "We provide preliminary data of responses to lifileucel and biomarkers in heavily pre-treated metastatic melanoma patients who have progressed on multiple checkpoint and BRAF/MEK inhibitors (if BRAF mutated)." (PMID 30400822, 2018). "Our findings suggest that eNAMPT is a novel marker of tumor burden and response to therapy in patients with metastatic melanoma carrying BRAF mutations." (PMID 29721178, 2018). "Vemurafenib, a potent BRAF protein kinase inhibitor, is reserved for the treatment of metastatic melanoma associated with BRAF V 600 mutation." (PMID 29492238, 2018). "Combination of the BRAF inhibitor dabrafenib with the MEK inhibitor trametinib has been shown to lead to a further improved overall survival in metastatic melanoma carrying the BRAF V600E mutation, as compared with dabrafenib monotherapy." (PMID 29654229, 2018). "Trametinib, a MEK 1/2 inhibitor, was FDA approved as a single agent (2013) and in combination with the BRAF inhibitor, dabrafenib (2014), for the treatment of patients with unresectable or metastatic melanoma with BRAF V600E or V600K mutations." (PMID 30326621, 2018). "BRAF inhibitor vemurafenib achieves high response rate and an improvement in survival in patients with BRAF-mutated metastatic melanoma." (PMID 29552321, 2018). "In this monocentric prospective study, samples from 19 patients with stage IV metastatic melanoma collected before and after treatment were assessed for BRAF and NRAS mutations." (PMID 30546839, 2018). "Recent European guidelines give less clear-cut recommendations for the management of BRAF-mutated metastatic melanoma patients, mentioning the possibility to use BRAFi in first or second-line therapy after anti-PD-1 failure." (PMID 29970025, 2018). "CfDNA is an essential source of material for management of metastatic melanoma patients as it allows detection of somatic targeting mutations (BRAF, KIT), copy number variations and the tumor mutation load." (PMID 30546839, 2018). "We sequenced vemurafenib with HD IL-2 in patients with BRAF-mutated metastatic melanoma to improve long term outcomes." (PMID 30053905, 2018). "Surgical resection of the large, hemorrhagic lesion showed metastatic melanoma with BRAF V600E mutation." (PMID 29520339, 2018).
metastatic melanoma (continued). "In comparison to using conventional SOP, using an FA-PCR platform for BRAF mutation analysis of patients with metastatic melanoma significantly reduced the delay in initiation of personalized therapy by 10 days." (PMID 30181812, 2018). "Patients with BRAF-mutated metastatic melanoma treated with inhibitors specific for the mutated BRAF as well as with additional mitogen-activated extracellular signal-regulated kinase (MEK) inhibitors benefit from these therapies." (PMID 30206212, 2018). "Vemurafenib, a BRAF inhibitor, is effective for treating patients with BRAF V600E mutation-positive inoperable and metastatic melanoma but this drug is associated with QT prolongation." (PMID 29876021, 2018). "More than 50% of metastatic melanoma patients have a specific mutation in the serine/threonine kinase BRAF." (PMID 29929490, 2018). "Binimetinib has also been evaluated in combination with encorafenib, a highly selective BRAF inhibitor, in patients with advanced or metastatic melanoma with BRAF driver mutations." (PMID 29455659, 2018). "We conducted a Phase II trial to assess the clinical activity of continued BRAF inhibition, with the addition of chemotherapy, in patients with BRAF-mutated metastatic melanoma and systemic PD during vemurafenib treatment as single agent." (PMID 29552321, 2018). "The use of BRAF (BRAF is a human gene that encodes a protein called B-Raf involved in sending signals inside cells that direct cell growth) kinase inhibitor in patients with BRAF mutated metastatic melanoma is one such recent example." (PMID 29329525, 2018). "Vemurafenib, the first targeted inhibitor for the BRAF mutant has been developed and approved for the treatment options for BRAF mutated metastatic melanoma." (PMID 30544544, 2018). "In conclusion re-challenge with a BRAF inhibitor is a meaningful therapeutic option for patients with BRAF V600-mutated metastatic melanoma." (PMID 30344946, 2018). "In this study, we used an FA-PCR platform to rapidly screen patients with advanced or metastatic melanoma for BRAF gene mutations." (PMID 30181812, 2018). "Trametinib, a highly specific and potent MEK1/2 inhibitor, is approved by the Food and Drug Administration (FDA) for the treatment of BRAF-mutated metastatic melanoma." (PMID 30185207, 2018). "Ulceration of the primary tumor and a BRAF mutation were moderately associated with worse survival in patients with metastatic melanoma treated with ipilimumab." (PMID 29177235, 2017). "Most importantly plexins are known to be down-regulated by oncogenic BRAF V600 in metastatic melanoma, thus confirming the relevance of this pathway underlined by our analysis." (PMID 28118616, 2017). "Currently, general advice is to test metastatic melanoma for the presence of BRAF mutation in the most recent metastatic sample." (PMID 28039443, 2017). "A final interesting study finding was that the presence of a BRAF mutation had a moderate increased risk of death while adjusting for ulceration, age, and institution in these patients (n=302) with metastatic melanoma." (PMID 29177235, 2017). "The EMA approved this combination a year later for adults with unresectable or metastatic melanoma with the BRAF V600 mutation." (PMID 28954413, 2017). "Single-agent vemurafenib and dabrafenib demonstrated unprecedented objective responses and improvements in progression-free and overall survival in patients with metastatic melanoma bearing BRAF V600E mutation, as compared to old chemotherapy approaches." (PMID 28118616, 2017). "A 55-year-old Caucasian patient was treated with nivolumab as a second line therapy for metastatic melanoma, affecting the lymph nodes and duodenum, harboring a BRAF V600E mutation." (PMID 29195497, 2017). "These attributes have provided the impetus for significant drug development efforts that target BRAF-mutated metastatic melanoma." (PMID 28052762, 2017).
metastatic melanoma (continued). "The targeted mitogen-activated protein kinase inhibitors benefit the minority (up to 40%) of metastatic melanoma patients whose diseases carry an oncogenic BRAF mutation." (PMID 28435677, 2017). "In these two reports, patients had BRAF wild-type metastatic melanoma managed with a first-line cytotoxic T-lymphocyte-associated protein 4 (CTLA-4) inhibitor (ipilimumab) with maintenance of the graft while on ipilimumab." (PMID 28315636, 2017). "For instance, vemurafenib, a selective inhibitor of V600E/K mutant BRAF, was first approved in metastatic melanoma, a cancer in which approximately 50% of tumors harbor a BRAF V600E/K mutation." (PMID 28115009, 2017). "Keytruda® was first approved by the FDA in 2014 for the treatment of patients with unresectable or metastatic melanoma and disease progression following ipilimumab and, if BRAF V600 mutation positive, a BRAF inhibitor." (PMID 28219375, 2017). "Pembrolizumab (Keytruda) was granted approval in 2014 for unresectable or metastatic melanoma and disease progression following ipilimumab and if found to have BRAF V600 mutation–positive disease, then a BRAF inhibitor is added to the regimen." (PMID 29900022, 2017). "Based on these findings and other preclinical evidence we conducted a Phase 1B Study to epigenetically modify BRAF-mutated metastatic melanoma by combining decitabine with vemurafenib." (PMID 29179510, 2017). "Vemurafenib and Dabrafenib are two FDA-approved specific BRAF inhibitors and that are used to treat metastatic melanoma patients with BRAF mutations." (PMID 29285312, 2017). "The resulting data supported clinical activity of binimetinib in patients with NRAS-mutated and BRAF-mutated metastatic melanoma." (PMID 28954413, 2017). "BRAF inhibitors (BRAFi) are standard of care for the treatment of BRAF V600 mutation-driven metastatic melanoma, but can lead to paradoxical activation of the mitogen-activated protein kinase (MAPK) signalling pathway." (PMID 28659148, 2017). "Top scoring drug trametinib is used for the treatment of unresectable or metastatic melanoma with BRAF V600E or V600K mutations." (PMID 27965461, 2017). "The drug was approved by FDA for the treatment of patients both with BRAF V600 wild-type unresectable and BRAF V600 mutation-positive metastatic melanoma in addition to combination treatment with ipilimumab (anti-CTLA-4 antibody)." (PMID 28445515, 2017). "An emerging option for metastatic melanoma with uncommon BRAF mutations is immunotherapy using checkpoint inhibitors such as PD-1 inhibitors or CTLA-4 inhibitors." (PMID 29181212, 2017). "In Europe and the USA, treatment options for first- or second-line treatment of BRAF-mutated metastatic melanoma include BRAF/MEK inhibitor combinations." (PMID 29176861, 2017). "The introduction of BRAF inhibitors such as vemurafenib and dabrafenib have yielded significantly improved outcomes in patients with metastatic melanoma with either BRAF V600E or V600K mutations." (PMID 28052762, 2017). "More recently, another MEK inhibitor, cobimetinib—when used in combination with the BRAF-inhibitor, vemurafenib—was reported to improve progression-free survival among patients with BRAF V600-mutated metastatic melanoma." (PMID 28474232, 2017). "Opdivo® was first approved by the FDA in 2014 for the treatment of patients with unresectable or metastatic melanoma and disease progression following ipilimumab and, if BRAF V600 mutation positive, a BRAF inhibitor." (PMID 28219375, 2017). "Overall there was a high consistency between the data relative to BRAF mutation observed in primary and matched metastatic melanoma." (PMID 28039443, 2017). "EGFR mutations or ALK rearrangements in lung cancer, BRAF V600E mutations in metastatic melanoma and breast cancer patients harbouring HER2 amplifications are examples of therapeutic biomarkers routinely used in the adult population." (PMID 29340109, 2017).